TOMM20L (translocase of outer mitochondrial membrane 20 like)
Synonyms: UNQ9438
Tractability: Antibody: UniProt predicts a signal peptide or a membrane-spanning region.
Gene: Protein-coding gene on chromosome 14 (58,395,928 to 58,408,702, forward strand). Ensembl gene ENSG00000196860.
Subcellular location: Mitochondrion outer membrane
Gene Ontology:
Molecular function: protein binding; protein transmembrane transporter activity
Biological process: protein import into mitochondrial matrix; tRNA import into mitochondrion; intracellular protein transport; protein targeting
Cellular component: mitochondrial outer membrane translocase complex; mitochondrial outer membrane
Genetic constraint (gnomAD): Loss-of-function variants: 14 observed, 13.77 expected, observed/expected ratio (o/e) 1.02, 90% interval 0.67 to 1.58. The upper end of that interval is the gene's LOEUF score, 1.58, which puts it in group 6 of 6, group 1 being the genes least tolerant of losing a copy. Missense variants: 195 observed, 146.97 expected, observed/expected ratio (o/e) 1.33, 90% interval 1.18 to 1.49. Synonymous variants: 71 observed, 57.26 expected, observed/expected ratio (o/e) 1.24, 90% interval 1.02 to 1.51.
Homologues: Orthologues: chimpanzee TOMM20L (98% identical), macaque TOMM20L (89% identical), pig TOMM20L (82% identical), rabbit TOMM20L (78% identical), dog TOMM20L (77% identical), rat Tomm20l (62% identical), mouse Tomm20l (61% identical), Caenorhabditis elegans tomm-20 (32% identical), Drosophila melanogaster Tom20 (32% identical), Drosophila melanogaster tomboy20 (28% identical). Paralogues in human: TOMM20 (41% identical).
Diseases named in the same sentence as TOMM20L in open-access papers:
TOMM20L is named in the same sentence as 1 disease in open-access papers, as found by Europe PMC text mining. Sharing a sentence is not in itself a finding about the gene and the disease. The quoted sentences say what the papers report.
glioblastoma (1 paper, 2023). The most malignant astrocytic tumor (WHO grade IV). "Eight genes, AC016737.2, BNC2-AS1, AC007040.1, AC009248.3, SOCAR, LAGE3, TOMM20L, and FP671120.11, were specific to patients with IDH1-wt and TERT-promoter-mutated glioblastoma." (PMID 37568598, 2023).